CCR4 (C-C motif chemokine receptor 4)
Diseases named in the same sentence as CCR4 in open-access papers (continued):
Sharing a sentence is not in itself a finding about the gene and the disease.
sarcoidosis (7 papers, 2012 to 2025). Sarcoidosis is a multisystemic disorder of unknown cause characterized by the formation of immune granulomas in involved organs. "This is the first study to demonstrate the association between the development of sarcoidosis and imbalance of circulating Tfh cells, especially CCR4− and CXCR3-expressing Tfh subsets." (PMID 31974463, 2020). "We noticed that, within CD45 RA–CCR7+ central memory Tregs, the frequency of CCR4+ CCR6+ CXCR3– Th17-like Tregs decreased in patients with sarcoidosis compared to the control group (26.65% (21.98; 32.04) vs. 32.59% (25.73; 38.39) with p < 0.01)." (PMID 37189479, 2023). "CXCR3− CCR6− Tfh2 and CXCR3− CCR6+ Tfh17 cells increased, while CXCR3+ CCR6− Tfh1 and CXCR3+ CCR6+ CCR4− Tfh17.1-like cells decreased in sarcoidosis patients." (PMID 33036432, 2020). "In blood, we observed Th17.0 (CCR6+CCR4+CXCR3−) cells with increased frequencies in sarcoidosis compared to health." (PMID 32774332, 2020). "TARC levels as well as the percentage of CCR4+ cells were higher in sarcoidosis patients with greater organ involvement and more advanced disease stages compared to patients with less severe disease." (PMID 33036432, 2020). "Patients with IPF have significantly higher CCR4 expression on BAL CD4 T cells compared to patients with other interstitial lung diseases such as sarcoidosis." (PMID 23705860, 2013). "To test this, we used flow cytometry to compare the T-bet-expressing frequencies in peripheral blood Th17.0 (RORγt+CCR6+CCR4+CXCR3−) cells between sarcoidosis subjects with different clinical trajectories defined by longitudinal changes in lung function and immunosuppression use." (PMID 32774332, 2020). "This is the first study to demonstrate the association of circulating imbalance Tfh cells, especially between CCR4− and CXCR3-expressing Tfh subsets in the development of sarcoidosis." (PMID 31974463, 2020).
bladder cancer (6 papers, 2015 to 2025). "Tregs in a canine bladder cancer model entered tumor tissue through the CCL17–CCR4 axis, and anti-CCR4 treatment significantly inhibited tumor growth and improved the survival rate." (PMID 38807592, 2024). "An in vitro model of bladder cancer, a partial decrease in the expression of CCR4 has been shown to facilitate metastasis, despite residual protein activity." (PMID 36268024, 2022). "In addition, CCR4 was highly expressed in tumor-infiltrating Tregs (TITRs) in human bladder cancer." (PMID 38807592, 2024).
colon carcinoma (6 papers, 2012 to 2025). "Indeed, CCL17/CCR4-dependent colon cancer cell migration is associated with increased activity of RhoA and can be inhibited by targeting Rho-kinase function." (PMID 28146427, 2017). "For example, chemokine receptor-modified T-cells (e.g., CCR4- and CCR6-engineered variants) selectively home to tumor-draining lymph nodes and intratumoral regions in murine colon cancer models, markedly improving therapeutic efficacy." (PMID 40746833, 2025). "Instead, in the MC38 colon carcinoma model, anti-tumoral efficacy as well as lymph node vs. tumor-homing patterns were mostly driven by CCR4 and CCR6, respectively." (PMID 37301772, 2023). "It was further shown that a CCR4 antagonist CCR4-351 inhibited Treg cell recruitment into tumor tissues in mice bearing murine pancreatic and colon cancers, and augmented tumor-specific immune responses." (PMID 34885241, 2021). "Here, significantly increased tissue concentrations of the CCR4-ligand CCL22 were also found in colonic tumors, and probably contribute to recruitment of CCR4+ cells." (PMID 22319577, 2012). "Our results show that CCR4+CTLA4hi Treg accumulate in colon tumors, while the frequencies of activated conventional Th1 type T cells are decreased." (PMID 22319577, 2012). "This study shows that CCR4+CTLA4hi Treg accumulate in colon tumors, while the frequencies of activated conventional Th1 type T cells are decreased." (PMID 22319577, 2012). "Based on the considerations above, we hypothesized that should be added after hypothesized miR-155-5p might regulate CCL17-induced and CCR4-dependent migration of colon cancer cells via RhoA function." (PMID 28146427, 2017). "However, Treg and conventional CD4+ T cells expressing CCR4, which is primarily expressed on Th2 type CD4+ T cells and Treg were accumulating in the colon tumors." (PMID 22319577, 2012).
diabetes (6 papers, 2020 to 2026). "Although, the diabetes-causing potential of CCR4-expressing T cells has been highlighted in an NOD mice model, another study suggests that recruitment CCR4-bearing Treg to the pancreatic islets may actually prevent murine autoimmune diabetes." (PMID 39011037, 2024). "Similar to this, prolonged inflammation in diabetes patients results in T-cell accumulation, which may be the cause of elevated levels of TNF- and C-C motif chemokine receptor 4 (CCR4) chemokines, which have a substantial impact on the immune response and facilitate disease progression." (PMID 36831151, 2023). "Our findings raise the possibility that disruption of the CCR4–NOT complex could be involved in the loss of β-cell identity in diabetes, possibly through de-repression of β-cell immature and disallowed genes." (PMID 32859966, 2020). "Consistent with this, a disruption of the CCR4–NOT complex might be pathogenic in diabetes." (PMID 32859966, 2020). "In conclusion, our work identifies CNOT3 as an important post-transcriptional regulator of β-cell identity and function, and raises the possibility that alterations in CNOT3 expression and/or dysregulation of the CCR4–NOT complex contribute to β-cell failure in diabetes." (PMID 32859966, 2020). "To investigate whether CCR4–NOT is a possible early effector in the pathogenesis of diabetes, we examined CCR4–NOT complex subunit expression in the prediabetic state using 20-week-old mice fed a high-fat diet (HFD) for 3 months." (PMID 32859966, 2020). "Our findings show that the CCR4–NOT complex is deregulated in pancreatic islets in diabetes, thus suggesting that the CCR4–NOT complex serves as a therapeutic target to treat diabetes." (PMID 32859966, 2020). "Earlier studies have revealed the involvement of the CCR4–NOT complex in development of metabolic disorders such as obesity, diabetes, and lipodystrophy;16–18 however, its role in maintaining normal β-cell function has not been investigated." (PMID 32859966, 2020). "Nevertheless, our findings suggest possible relationship between CCR4–NOT complex dysfunction and diabetes (both T1D and T2D)." (PMID 32859966, 2020).
glioblastoma (6 papers, 2015 to 2025). The most malignant astrocytic tumor (WHO grade IV). "The CCL2/CCR2/CCR4 pathway exerts immunomodulatory effects on glioblastoma through the recruitment of CCR2+ GAMs, CCR2+ MDSCs and CCR4+ Tregs, and these immunosuppressive cells can contribute to immune escape by attenuating the effector T cell response." (PMID 33803414, 2021). "Collectively, these studies highlight a key role for the CCL2 ligand and both of its receptors (CCR2 and CCR4) in promoting the recruitment of immunosuppressive myeloid and Treg populations to glioblastoma." (PMID 33803414, 2021). "We also observed high levels of CCL2 in supernatants from dissociated glioblastoma biopsies and GNS cells, inferring that CCL2 could recruit T cells through CCR2 or CCR4 to glioblastoma." (PMID 35464424, 2022). "In glioblastoma, tumor cells can secrete chemokines such as C-C motif chemokine ligand 22 (CCL22), which binds to the C-C chemokine receptor type 4 (CCR4) receptor on the surface of Tregs, thereby recruiting Tregs and enhancing immunosuppression." (PMID 41188782, 2025). "Within glioblastoma-infiltrating T cells, a large proportion of cells were positive for CXCR4 and the proportion of cells positive for chemokine receptors CCR4, CCR5, CCR6, CCR7, CXCR3, and CXCR6 ranged between 5-25%." (PMID 35464424, 2022). "The CCR4 chemokines were not selected for further analysis as we observed low proportions of non-lymphocyte cell populations expressing the complementary chemokines CCL17 and CCL22 via scRNA-seq and observed no enrichment of CCR4+ T cells in glioblastoma." (PMID 35464424, 2022). "Thus, our findings now suggest that high CCL2 abundance identified by multiple glioblastoma studies may mediate trafficking to glioblastoma through CCR2 rather than CCR4." (PMID 35464424, 2022). "CCR4+ cells were most abundant within the CD8+ Tcm population, but expression of this receptor in glioblastoma samples was not enriched for any CD8+ T-cell subsets compared to matched blood samples." (PMID 35464424, 2022). "However, here we show that T cells are more likely to be recruited via CCR2 than CCR4 given that both CCR2+ Tregs, and CCR2+ Tcm cells were enriched in glioblastoma tissues, and we found no enrichment of CCR4+ T cells in glioblastoma." (PMID 35464424, 2022).
lupus (6 papers, 2009 to 2025). "For patients with lupus in particular, an increase in CCR4-expressing Th2 cells are increased in patients with active disease and is thought to play a role in the development of autoantibodies contributing to disease pathogenesis." (PMID 32973504, 2020). "The putative ability of hydroxychloroquine to inhibit CCR4 signal transduction likely explains its efficacy in the treatment of rheumatoid arthritis and lupus." (PMID 32973504, 2020). "We noticed a strong correlation between the frequencies of CD4+IL-17+ T cells and CD4+CCR4+CCR6+ T cells in the peripheral blood of lupus patients." (PMID 20334681, 2010). "Our data offer a scientific rationale for exploring the utility of Th17 cells, as well as Th17-associated molecules CCR4 and CCR6 as biologic markers for disease activity in human lupus." (PMID 20334681, 2010). "Of interest, CD4+CCR4+CCR6- T cells also appeared to expand in active lupus patients." (PMID 20334681, 2010). "In patients with rheumatoid arthritis and lupus, the percentage of circulating CD4+/CCR4+ T cells is significantly elevated relative to heathy controls." (PMID 32973504, 2020). "In the present study, we investigated the expression of chemokine receptors, CXCR3, CCR5, CCR4, and CCR3, in the surface of probiotic-maturated tolerogenic DCs (matured by L. rhamnosus and L. delbrueckii) with monocyte origin to find the effect of these probiotics on migratory lupus-DC patterns." (PMID 35317107, 2021).
multiple sclerosis (6 papers, 2006 to 2023). A progressive autoimmune disorder affecting the central nervous system resulting in demyelination. "Since CCR4 has been associated with a Th2 phenotype, CSF levels of CCR4 were analyzed in six patients with multiple sclerosis (MS), a disease associated with Th1 responses in the CNS." (PMID 16824229, 2006). "CCR4 regulates the function of inflammatory macrophage in many inflammatory disorders including multiple sclerosis; CCR4 knockout mice show delayed disease progression." (PMID 37761018, 2023). "Increasing evidence from clinical trials indicates the involvement of the CCL17/CCL22/CCR4 axis in the pathogenesis of multiple sclerosis." (PMID 36555280, 2022). "Expression of CCR2, CXCR3 and CCR4 on CD4+ T or CD8+ T cells in blood and cerebrospinal fluid (CSF) for multiple sclerosis (MS) was measured by 3-color flow cytometry, and compared to blood from healthy controls and CSF from patients with other inflammatory neurological diseases (INDs)." (PMID 19662226, 2007).
Obesity (6 papers, 2019 to 2025). Accumulation of substantial excess body fat. "It is also necessary to replicate these results in larger groups of obese people in order to assess the significance of CCR4 in mediating vascular dysfunction and its connection to metabolic complications associated with obesity." (PMID 37124725, 2023). "As a result, the CCL22/CCR4 axis represents a promising therapeutic target for preventing the development of obesity and other metabolic disorders, such as insulin resistance." (PMID 38924414, 2024). "In our study, we observed potential beneficial effects of CCR4 blockade in the context of obesity, since treatment with a neutralizing antibody against CCR4 led to a decrease of endothelial cell proliferation and differentiation." (PMID 37124725, 2023). "Thus, CCL22, through its interaction with its receptor CCR4, establishes the local microenvironment to regulate adipose beiging and energy homeostasis, offering therapeutic potential for preventing obesity and related metabolic disorders." (PMID 38924414, 2024). "Based on these findings, pharmacological modulation of the CCR4 axis could represent a new therapeutic approach to prevent adipose tissue dysfunction in obesity." (PMID 37124725, 2023). "Our work establishes previously unrecognized biological pathways, including MDC CCL22, its receptor CCR4 in eosinophils, and the upstream influence of LNs in the differentiation of APCs into beige adipocytes, as well as their role in maintaining whole-body energy balance and obesity prevention." (PMID 38924414, 2024). "Future in vivo studies in an animal model of obesity are required to delineate the potential benefit of altering the CCR4/CCL17/CCL22 signalling in vivo and assess the therapeutic window of CCR4 inhibition." (PMID 37124725, 2023). "Importantly, the CCR4–NOT complex is implicated during development of metabolic diseases such as obesity, diabetes, liver steatosis, and energy metabolism by metabolizing mRNAs of energy metabolic-associated genes and thus reducing their expression levels through deadenylase activity." (PMID 31482095, 2019). "While several subunits within the CCR4-NOT complex were shown to be involved in obesity and energy metabolism, the roles of CNOT4 in obesity remain unexplored." (PMID 40424271, 2025). "Previous reports on gene knockout mice of CCR4-NOT components, such as CNOT3, CNOT6L and CNOT7, have demonstrated that CCR4-NOT complex plays roles in suppressing diet-induced obesity and improving metabolic disorder through degradation of target mRNAs." (PMID 40424271, 2025). "Thus, Cnot4 is unlikely to function as a recruiter of mRNAs for CCR4-NOT complex to deadenylate in the context of HFD-induced obesity." (PMID 40424271, 2025). "Thus, while the significance of CCR4-NOT complex in regulating metabolic genes in liver and adipose tissues has been proposed, the roles of CNOT4 in obesity are elusive." (PMID 40424271, 2025).
renal cell carcinoma (6 papers, 2014 to 2025). "High CCR4 expression in the tumour or its microenvironment is a poor prognostic indicator in lung adenocarcinoma, renal cell carcinoma, gastric, breast, and oral tongue cancer." (PMID 38256152, 2024). "C–C motif chemokine 22 (CCL22), a chemokine that acts on CCR4 + cells such as dendritic and T cells, participated in the progression of renal cell carcinoma and showed a connection with circ_0039569 and miR-34a-5p." (PMID 35831825, 2022). "Binding to murine CCR4 was additionally confirmed in the flow cytometry experiments using CCR4+ murine renal cell carcinoma cell line Renca and the mouse splenocytes, which express CCR4 upon activation via CD3 and CD28." (PMID 25080123, 2014). "Molecular docking findings indicate that the environmental endocrine-disrupting chemical BPA specifically interacts with key targets essential for the function of renal cell carcinoma cells, including CHRM3, GABBR1, CCR4, KCNN4, PRKCE, CYP2C9, HPGD, and FASN." (PMID 41301871, 2025).
type 1 diabetes (6 papers, 2014 to 2024). "Additional studies are needed to ascertain the precise relevance of CCR4 on specific immune cell subsets in the pathogenesis of type 1diabetes." (PMID 39011037, 2024). "Similarly, an effector memory Treg subset expressing HLA-DR, CCR4, CCR6, CXCR3, and GATA3 was increased in the high-risk group of patients with type 1 diabetes." (PMID 37189479, 2023). "A reduced frequency of CCR4+ CD3+ cells was observed among recently-diagnosed type 1 diabetics." (PMID 30405601, 2018).
influenza (5 papers, 2016 to 2022). An acute viral infection of the respiratory tract, occurring in isolated cases, in epidemics, or in pandemics; it is caused by serologically different strains of viruses (influenzaviruses) designated A, B, and C, has a 3-day incubation period, and usually lasts for 3 to 10 days. "Although in influenza-infected mice, expression of CCL17 and CCL22 by airway epithelial cells is associated with imprinting of CCR4+CD4+ T cells by lung dendritic cells, our findings suggest that this does not occur with human RSV." (PMID 31815739, 2020). "It has been reported that CCR4 is required for optimal T cell-mediated protection from influenza in mice, and surface CCR4 expression has been observed on lymphocytes isolated from lung and bronchoalveolar lavage fluid." (PMID 31801624, 2019). "In mice, expression of CCR4 on T cells imprints them to home to the lungs upon influenza infection." (PMID 28640917, 2017). "Extensive surface phenotyping was performed together with combinatorial tetramer staining to measure the frequency, memory status (CD45RA and CCR7), chemokine receptor expression (CXCR3, CCR4, CCR6 and CXCR5) as well as activation status (CD38) of these influenza-specific T cells." (PMID 27571776, 2016).
multiple myeloma (5 papers, 2017 to 2023). "In contrast the frequency of CCR4-expressing CD4+ T cells in BM was substantially increased in patients with myeloma to an average expression of 20% of the CD4+ T cell pool (**p = < 0.01)." (PMID 28389623, 2017). "Some of these alterations were striking with the proportion of bone marrow CD4 and CD8+ T cells which expressed CCR4 being increased from 4.4% and 3% respectively in the control group to 20% and 12% in patients with myeloma." (PMID 28389623, 2017). "The data showed that the levels of CCR1 and CCR5, but not CCR4, were significantly increased on the HSPCs of myeloma patients compared to healthy donors (CCR1: 5.13% ± 1.32% vs. 0.85% ± 0.24%, p = 0.0096; CCR5: 5.72% ± 1.57% vs. 1.91% ± 0.37%, p = 0.0199)." (PMID 33239656, 2020). "It was noteworthy, however, that the frequency of CCR4+ T cells was substantially greater than the CXCR3+ population, suggesting that CCR4-binding chemokines may have a predominant influence on recruitment and retention of T cells to marrow in patients with myeloma." (PMID 28389623, 2017).
osteosarcoma (5 papers, 2008 to 2022). A usually aggressive malignant bone-forming mesenchymal neoplasm, predominantly affecting adolescents and young adults. "A recent study revealed that both CCR2 and CCR4 are highly expressed and involved in patients with osteosarcoma." (PMID 33228783, 2020). "In this study, CCR2 instead of CCR4 was involved in osteosarcoma migration in vitro." (PMID 33228783, 2020). "However, in another study, CCR4 was found in 21 out of 22 osteosarcoma samples." (PMID 33228783, 2020). "In the migration assay, osteosarcoma cell migration was remarkably reduced by the CCR2 inhibitor but not by the CCR4 inhibitor." (PMID 33228783, 2020). "Through clinical screening and functional evaluation, CCR4–NOT transcription complex subunit 1 (CNOT1) correlated with the growth of osteosarcoma cells." (PMID 28188704, 2017). "Although tumor vessels normally do not show a distinct smooth muscle layer, CCR4 expression in the osteosarcoma samples is suggestive of an involvement of this receptor in neoangiogenesis in this tumor." (PMID 18215331, 2008). "Through clinical analysis and functional screening, CNOT1, a member of the human CCR4–NOT deadenylase complex, was found to be related to osteosarcoma proliferation." (PMID 28188704, 2017).